HSPH1 (heat shock protein family H (Hsp110) member 1)
Diseases named in the same sentence as HSPH1 in open-access papers (continued):
Sharing a sentence is not in itself a finding about the gene and the disease.
tumor (continued). "On the contrary, further work demonstrated inhibittory effects of extracellular HSPH1 and HYOU1 upon macrophage differentiation, favoring a pro-tumor phenotype." (PMID 28468249, 2017). "Additionally, genes involved in the cellular response to stress were commonly upregulated in tumor C1 and C2 NK cells (HSP90AA1, HSPA1B, HSPH1, DNAJB1, PSMB9, CSTP1)." (PMID 41082397, 2026). "The heatmap showed that 12 tumor suppressors formed into two clusters: cluster 1 contains seven downregulated tumor suppressors including PTEN, PSME1, DNAJB1, HSPH1, DEDD2, PAK1IP1, and MIR1244-3; and cluster 2 contains five upregulated tumor suppressors (OSGIN1, IFI27L1, MTCH2, NKD2, and IBTK)." (PMID 34571936, 2021). "Additionally, ATAC peak profiles for target genes in patient recurrent tumor samples, showed proximal gene linkages in clusters mediating the progenitor_photoreceptor signature and cycling progenitors for regulators such as NFE2L2, HLX, HSPH1, and KDM4B." (PMID 39711559, 2024).
cancer (47 papers, 2004 to 2026). A tumor composed of atypical neoplastic, often pleomorphic cells that invade other tissues. "First, we analysed the characterisation of HSPH1, including its chromosomal and subcellular localisation, using online databases and found that HSPH1 was highly associated with a variety of cancers through gene-disease network interaction analysis." (PMID 40395325, 2025). "HSP90 and HSP110 (encoded by Hsph1) have been reported to regulate the growth of cancer cells through STAT3 activation." (PMID 38336777, 2024). "HspH1 overexpression has also been shown to correlate with elevated nuclear β-catenin protein levels and upregulation of Wnt genes implicated in cancer." (PMID 33525518, 2021). "A previous study demonstrated that HspH1 is a component of the β-catenin degradation complex which is implicated in cancer signaling." (PMID 33525518, 2021). "A more detailed examination of HSPH1 in NSCLC will assist in determining the precise mechanism through which HSPH1 contributes to cancer development, thereby enhancing the potential for utilising HSPH1 in clinical settings." (PMID 40395325, 2025). "A pan-cancer analysis based on the TIMER database also confirmed that HSPH1 expression was significantly elevated in several cancers." (PMID 40395325, 2025). "Cancer cells modulate cellular metabolism and heavily rely on chaperones like HSPH1, as this protein has anti-aggregation properties and can modify the misfolded proteins, and thus cell can sustain cellular stress and survive." (PMID 38992681, 2024). "Previous studies have demonstrated the pivotal inhibitory effects of HSPA5, HSPB1, HSF1 and HSPH1 in cancer ferroptosis." (PMID 38041016, 2023). "As such, HspH1 upregulation accompanied with hyperactivation of Wnt signaling may pose as important prognostic biomarkers of cancer." (PMID 33525518, 2021). "The expressions of five HSPs members (HSPH1, HSPD1, SERPINH1, HSPA4 and HSP90AA1) in more than 20 types of cancers were detected and compared with expressions in normal tissues using the ONCOMINE database." (PMID 32523426, 2020).
infection (7 papers, 2011 to 2024). The state of being infected such as from the introduction of a foreign agent such as serum, vaccine, antigenic substance or organism. "Interestingly, in cluster 3 of DEGs between normal + infection group and undernutrition 75% + infection group, hub genes Dnaja1 (0.49-fold change), Hspa1a (0.12-fold change), Hspa1b (0.20-fold change) and Hsph1 (0.35-fold change) were also downregulated in undernutrition 75% + infection group." (PMID 38185681, 2024).
HSPH1 also shares sentences with these, for which no sentence is quoted: neurodegenerative disease (6 papers); Parkinson disease (5); gastric cancer (4); protein misfolding diseases (3); pulmonary arterial hypertension (3); cervical cancer (2); cutaneous melanoma (2); hyperglycaemia (2); injury (2); leukemia (2); non-Hodgkin lymphoma (2); oral squamous cell carcinoma (2); prion disease (2); renal cell carcinoma (2); squamous cell carcinoma (2); amyotrophic lateral sclerosis (1); asthma (1); autoimmune uveitis (1); Autoimmunity (1); basal cell carcinoma (1); Birt-Hogg-Dube syndrome (1); bladder cancer (1); brain cancer (1); Canavan disease (1); classical Hodgkin lymphoma (1); CNS tumors (1); colorectal tumor (1); COVID-19 (1); endometrial cancer (1); endothelial dysfunction (1).
A further 35 diseases each share a sentence with HSPH1 in 1 paper.